FAM106A (family with sequence similarity 106 member A)
Synonyms: FLJ11800; TL132; USP32P2; CCDC144B; CCDC144BP
Gene: Long non-coding RNA gene on chromosome 17 (18,511,221 to 18,625,681, reverse strand). Ensembl gene ENSG00000273018.
Diseases named in the same sentence as FAM106A in open-access papers:
FAM106A is named in the same sentence as 5 diseases in open-access papers, as found by Europe PMC text mining. Sharing a sentence is not in itself a finding about the gene and the disease. The quoted sentences say what the papers report.
osteosarcoma (2 papers, 2022 to 2025). A usually aggressive malignant bone-forming mesenchymal neoplasm, predominantly affecting adolescents and young adults. "FAM106A has been reported to be associated with multiple cancers including osteosarcoma, colorectal adenocarcinoma, and breast cancer." (PMID 41387767, 2025). "In osteosarcoma, FAM106A has been reported to trans-regulate the coding gene AL023806.1 through the transcription factor ZNF169." (PMID 41387767, 2025).
colorectal adenocarcinoma (1 paper, 2025). The most common type of colorectal carcinoma. "The expression of FAM106A has been reported to be down-regulated in colorectal adenocarcinoma cells exposed to the probiotic Lactobacillus acidophilus L-92." (PMID 41387767, 2025).
infection (1 paper, 2024). The state of being infected such as from the introduction of a foreign agent such as serum, vaccine, antigenic substance or organism. "Additionally, FAM106A interacts with SARS-CoV-2 and is downregulated after infection, at least in lung-epithelial cells 21–23." (PMID 39315271, 2024).
FAM106A also shares sentences with these, for which no sentence is quoted: breast carcinoma (1 paper); cancer (1).